TEX101 (testis expressed 101)
Diseases named in the same sentence as TEX101 in open-access papers (continued):
Sharing a sentence is not in itself a finding about the gene and the disease.
cancer (9 papers, 2012 to 2025). A tumor composed of atypical neoplastic, often pleomorphic cells that invade other tissues. "Alongside these genes of interest, it has been observed that both TEX101 and many of the interactome genes are associated with various cancer types with specific functional characteristics." (PMID 35774118, 2022). "We hypothesise that lower levels of serum TEX101, prior to diagnosis, could indicate a loss of basophil function leading to a reduction of detection systems for early-stage cancers." (PMID 35774118, 2022). "There is a growing body of evidence that TEX101 is associated with multiple forms of cancer." (PMID 35774118, 2022). "Among them, testicular expression protein 101 (TEX101), a cancer/testicular antigen family member, was initially identified in mouse testes and was subsequently found to be expressed in human and bovine germ cells." (PMID 36624393, 2023). "There are genes amongst the TEX101 interactome that are also involved in the progression and development of cancers." (PMID 35774118, 2022). "TEX101 refers to a new carcinoma-correlated protein, with a probably promising application to be a marker in terms of HNSCC prognosis/diagnosis." (PMID 34966825, 2021). "More recently, the expression and behavior of TEX101 in cancer were also investigated and showed potential significance for cancer progression." (PMID 25418358, 2014). "Recently, the metastasis suppressor function of TEX101 in cancer was disclosed, but the comprehensive investigation of its expression has rarely been reported." (PMID 25418358, 2014). "We also cover studies connecting TEX101 interactome to other forms of cancer, to acquire knowledge about mechanisms that could be of relevance for TGCT development." (PMID 35774118, 2022). "Aside from these connections to various cancer types and to male subfertility, TEX101 has to our knowledge not been associated with other disorders." (PMID 35774118, 2022). "In addition, the widespread tumor-specific expression of TEX101 suggests that it may play a part in the molecular process of carcinogenesis or may just be a byproduct of hypomethylation in cancer." (PMID 39208330, 2024). "TEX101, belonging to the same family with TEX10, was also documented in several tissues' carcinoma cell in HNSCC patients, while the general squamous epithelium had the immunonegative characteristic." (PMID 34966825, 2021). "For both patients and cell lines, cancer testis genes of TSGA10, TEX101 and ODF3 were determined by RT-PCR." (PMID 23396665, 2012). "SYCP1 and SYCE1 maintained modest inverse correlations, whereas PRSS54 and TEX101 showed no significant methylation-expression relationship, highlighting the cancer-specific nature of these epigenetic interactions." (PMID 41411337, 2025). "Both TEX101 and LY6K are known to be soluble in serum, an important characteristic shared with several other GPI-APs that are already useful biomarkers for various cancer types." (PMID 35774118, 2022).
tumor (6 papers, 2012 to 2025). "The associations between TEX101 expression and tumor grade and stage are an important area for further research." (PMID 39208330, 2024). "Thus, some genes within the interactome of TEX101 are related to tumour suppression, and some are associated with oncogenesis." (PMID 35774118, 2022). "DMRTC2 maintained similar methylation levels in both BC tumor and normal breast samples (~0.77 vs. ~ 0.78), whereas TEX101 was modestly higher in BC tissues (~0.46 vs. ~ 0.36)." (PMID 41411337, 2025). "In particular PRSS21, which is associated with TEX101 in curated databases, has been shown to be involved in initiation and progression of TGCT and is thought to act as a tumour suppressor." (PMID 35774118, 2022).
hematological malignancies (1 paper, 2025). "ADAD1 showed a neutral correlation, while TEX101 displayed a slight positive trend, suggesting context-dependent regulation in hematological malignancies." (PMID 41411337, 2025).
TEX101 also shares sentences with these, for which no sentence is quoted: cancer testis (2 papers); prostate carcinoma (2); colon cancer (1); germ cell tumor (1); head and neck carcinoma (1); mastitis (1); Obstructive azoospermia (1); varicocele (1).